G6PD (glucose-6-phosphate dehydrogenase)
Diseases named in the same sentence as G6PD in open-access papers (continued):
Sharing a sentence is not in itself a finding about the gene and the disease.
G6PD deficiency (continued). "Severe hemolysis is an uncommon complication but has been reported in patients with glucose-6-phosphate dehydrogenase (G6PD) deficiency." (PMID 34188961, 2021). "Screening for CF was included in the NBS of North Macedonia, Bulgaria screened for congenital adrenal hyperplasia (CAH), Greece screened for glucose-6-phosphate dehydrogenase (G6PD) deficiency and classic galactosemia (GALT)." (PMID 34026686, 2021). "In the 12 neonates with G6PD deficiency of normal bilirubin level (control group), G6PD gene mutations were identified in 9 cases, including c.1376G > T (5 cases), c.1388G > A (2 cases), c .1024C > T (1 case), and c.95A > G (1 case)." (PMID 34895177, 2021). "This is the first nationwide survey of G6PD genotyping that addresses the relation between ethnic origin and G6PD deficiency in Mauritania." (PMID 34451395, 2021). "In the neonates with hyperbilirubinemia, the bilirubin level of 74 cases of G6PD deficiency was 334.43 ± 79.27 μmol/L, which was markedly higher than that of neonates with normal G6PD (300.30 ± 68.62 μmol/L)." (PMID 34895177, 2021). "Glucose-6-phosphate dehydrogenase (G6PD) deficiency is the most common hereditary disorder in humans, found mainly in people of Mediterranean, Southeast Asian, and African descent and affecting over 400 million people." (PMID 34949182, 2021). "Glucose-6-phosphate dehydrogenase (G6PD) deficiency (OMIM 300908) is the most common X-linked inherited erythroenzymopathy in Thailand." (PMID 33628497, 2021). "Methemoglobinemia can occur as a rare complication of treatment with rasburicase, primarily in patients with glucose-6-phosphate dehydrogenase (G6PD) deficiency." (PMID 33987056, 2021). "In this study, the genotyping of the G6PD gene and the genotype-phenotype correlation among 102 pediatric patients affected with G6PD deficiency was characterized in Phramongkutklao Hospital, a tertiary care center in central Thailand." (PMID 33628497, 2021). "Whole blood G6PD deficiency was screened by the fluorescent spot method, and erythrocyte G6PD activity was determined using a quantitative assay." (PMID 34949182, 2021). "In this study, we aimed to characterize the genotype-phenotype correlation of the G6PD mutation in 102 unrelated Thai pediatric patients affected with G6PD deficiency including 73 males (71.6%) and 29 females (28.4%)." (PMID 33628497, 2021). "Genetics has been known to affect drug metabolism since the discovery of glucose-6-phosphate dehydrogenase (G6PD) deficiency." (PMID 33995067, 2021). "The present study is the first to report the prevalence of G6PD deficiency and G6PD mutations in the Mon-Khmer or Lao Theung ethnic group." (PMID 33413378, 2021). "With the global spread of COVID-19, especially in regions with a high prevalence of G6PD deficiency, these cases should alert physicians to the possible correlation between G6PD-deficiency and hydroxychloroquine treatment." (PMID 33375707, 2020). "For example, glucose-6-phosphate dehydrogenase (G6PD) deficiency can result in jaundice secondary to hemolysis." (PMID 33118947, 2020). "In spite of the vast nutritional and environmental benefits provided by fava bean (Vicia faba), the ingestion of vicine/convicine provokes an acute hemolytic anemia called favism in individuals with a glucose-6-phosphate dehydrogenase (G6PD) deficiency." (PMID 32051767, 2020). "The major genetic determinant of G6PD deficiency in coastal Kenyan populations is the rs1050828 G>A mutation, which gives rise to a form of G6PD deficiency that is commonly referred to as the G6PD A− variant." (PMID 32536341, 2020). "Taken together these data summarized the main findings characterizing the drug induced acute hemolysis in subjects with G6PD deficiency, supporting the role of Fyn as key regulator of G6PD activity in red cells." (PMID 32863204, 2020). "G6PD B genotype was the most common (n=24), accounting for 88.88% of all cases with G6PD deficiency." (PMID 33214970, 2020).
G6PD deficiency (continued). "The drug is contraindicated in persons with a known case of retinopathy, hypersensitivity to HCQ or 4-aminoquinoline compounds, glucose-6-phosphate dehydrogenase (G6PD) deficiency, and pre-existing cardiomyopathy and cardiac rhythm disorders." (PMID 32789084, 2020). "Glucose-6-phosphate dehydrogenase (G6PD) deficiency is the most common X-linked genetic disease in the world with up to 400 million individuals affected." (PMID 33154437, 2020). "These G6PD small-molecule activators will be promising cures for G6PD deficiency diseases through boosting the enzymatic activity of the remaining G6PD protein." (PMID 32102234, 2020). "In this study, among the participants with G6PD deficiency, we found 19.2% to harbor the G6PD A- allele (G202/A376), which is associated with the reduced enzyme activity." (PMID 32802082, 2020). "Children with G6PD deficiency secondary to the G6PD A− variant have increased risk of SMA in this population." (PMID 32536341, 2020). "Diagnosis of G6PD deficiency at this level of enzyme activity requires the use of a quantitative G6PD assay." (PMID 32407682, 2020). "One study from the Duke University Medical Center in 2017 found that out of 275 patients taking hydroxychloroquine with measured G6PD levels, only 11 (4.0%) patients were determined to have G6PD deficiency." (PMID 32884875, 2020). "Some studies have shown that G6PD normal are more vulnerable to Plasmodium falciparum malaria than the G6PD deficiency and heterozygous individuals, whereas others have reported an equal vulnerability among the various G6PD types." (PMID 32646433, 2020). "P = 0.05) and children with G6PD deficiency had lower haemoglobin levels (9.7 g/dl [95% CI 9.4, 10.0]) than those with G6PD wild-type genotype (10.0 g/dl [95% CI 9.9, 10.2]; adj." (PMID 32420456, 2020). "While well tolerated in the majority of recipients, standard dosing of either drug can cause severe haemolysis in patients with glucose-6-phosphate dehydrogenase (G6PD) deficiency." (PMID 32407380, 2020). "G6PD A− is a WHO class 3 G6PD deficiency variant, predicted to result in only mild-to-moderate enzymatic deficiency (10–60% of normal)." (PMID 32536341, 2020). "Most of the malaria cases were caused by P. vivax and it is well known that the PQ used for the P. vivax treatment can induce haemolytic crises in individuals with glucose 6-phosphate dehydrogenase (G6PD) deficiency." (PMID 32299449, 2020). "rs1050829 is a WHO class 4 G6PD deficiency variant, predicted to result in a clinically asymptomatic decrease in G6PD enzymatic activity (< 40% reduction from wild type)." (PMID 32536341, 2020). "These uses raise concerns about its safe use in the setting of glucose-6-phosphate dehydrogenase (G6PD) deficiency, especially as 11% of African American men carry the G6PD A- variant." (PMID 33007039, 2020). "One involved harmonisation of levofloxacin with regards to use during pregnancy and in patients with glucose-6-phosphate dehydrogenase (G6PD) deficiency and one concerned oral formulation of fosfomycin in children younger than 12 years." (PMID 33183406, 2020). "Though the effects of high doses over prolonged periods was not assessed, this study provides early, novel safety data of the use of HCQ in the setting of G6PD deficiency secondary to G6PD A-." (PMID 33007039, 2020). "Drug-induced hemolytic anemia can occur in patients with glucose-6-phosphate-dehydrogenase (G6PD) deficiency." (PMID 32884875, 2020). "Notwithstanding on-going uncertainty regarding the exact nature of the balancing selection at the G6PD locus driven by malaria, there is a clear and reproducible association between G6PD deficiency and risk of SMA." (PMID 32536341, 2020). "The sequelae of these oxidative stresses are particularly alarming and life-threatening in people comorbid with glucose-6-phosphate dehydrogenase (G6PD) deficiency." (PMID 32802082, 2020).
G6PD deficiency (continued). "The sex-linked differences in G6PD deficiency and limitations of current G6PD diagnostic tools have led to a disparity in accurate G6PD diagnosis in females." (PMID 32766454, 2020). "G6PD deficiency is one of the common etiological factors for infant pathological jaundice and the G6PD variants are the major reason for the D-G6PD in China." (PMID 32680472, 2020). "For G6PD deficiency, there were six G6PD mutations and 19 genotypes were detected, including six kinds of heterozygotes, six kinds of hemizygotes, and seven kinds of homozygotes." (PMID 31793705, 2020). "In keeping with this, we observed a malaria-dependent increase in risk of pneumococcal bacteremia among children with G6PD deficiency secondary to the G6PD A− variant." (PMID 32536341, 2020). "G6PD deficiency is X-linked and thus subject to random X-chromosome inactivation in women giving them mosaic expression of G6PD activities in their individual cells." (PMID 32552815, 2020). "Our previous epidemiological screening of inherited blood disorders revealed the common G6PD deficiency genotype in the Bioko population was G6PD A‐ (V68M and N126D), with 8.7% prevalence." (PMID 31872983, 2020). "Our data is the first report of the incidence of G6PD gene variants in infants with G6PD deficiency and pathological jaundice in the southeastern area of China." (PMID 32680472, 2020). "In such cases, diagnosis of patients for glucose-6-phosphate dehydrogenase deficiency (G6PD) is essential." (PMID 30984417, 2019). "This drug is known to provoke acute hemolytic anemia in individuals with glucose-6-phosphate dehydrogenase (G6PD) deficiency." (PMID 31525211, 2019). "Low Hb levels in G6PD deficient patients with sickle cell anaemia (HbSS) and the association of reduced erythrocyte lifespan with G6PD deficiency have also been observed previously." (PMID 30819192, 2019). "Congenital causes of hemolysis includes enzymopathy like glucose 6 phosphate dehydrogenase (G6PD) deficiency, several hemoglobinopathy like sickle cell anemia (SCA) and thalassemias." (PMID 31703724, 2019). "Glucose-6-phosphate dehydrogenase (G6PD) deficiency is a genetic disorder and affects more than 400 million people in the world." (PMID 30673054, 2019). "This is potentially a major limitation in areas where G6PD deficiency is prevalent and quantitative G6PD assessments are unavailable." (PMID 30952158, 2019). "Glucose-6-phosphate dehydrogenase (G6PD) deficiency is the most common enzyme deficiency worldwide, with genetic variants resulting in a range of phenotypes that vary from asymptomatic to severe hemolysis." (PMID 31321386, 2019). "The prevalence of G6PD deficiency is expressed in terms of hemizygous males with a G6PD-deficient allele." (PMID 30184203, 2019). "Analysis of the association between haemoglobin (Hb) levels and G6PD deficiency in this study showed that mean Hb levels were similar in G6PD deficient children, G6PD heterozygous female children and G6PD normal children." (PMID 30819192, 2019). "The low prevalence of individuals carrying the G6PD A− variant, associated with moderate G6PD deficiency, detected in this study concurs with data from a recent study conducted in neighbouring Limpopo Province." (PMID 31234865, 2019). "It is estimated that over 400 million people are G6PD deficient globally; making G6PD deficiency the most common human enzymopathy." (PMID 30819192, 2019). "WHO recommends the use of primaquine after screening for G6PD deficiency, but in most malaria endemic countries, reliable G6PD testing is unavailable." (PMID 31327563, 2019). "Primaquine however has a haemolytic effect in G6PD deficient patients and therefore a routine test for G6PD deficiency before providing treatment is essential, which adds an additional layer of challenges." (PMID 31221145, 2019).
G6PD deficiency (continued). "Like primaquine, tafenoquine can cause severe hemolysis in persons with glucose-6-phosphate dehydrogenase (G6PD) deficiency and quantitative G6PD testing is required before prescribing." (PMID 31751320, 2019). "It will now become operationally easier to identify women and girls across the broad range of G6PD deficiency, collect safety data associated with females with intermediate G6PD activity and, in turn, provide appropriate treatment for these patients." (PMID 30184203, 2019). "The most consequential example is favism in individuals with glucose-6-phosphate dehydrogenase (G6PD) deficiency, which affects about 400 million people worldwide." (PMID 31781363, 2019). "The risks of giving PQ to G6PD-deficient patients in Nepal remain uncertain, although the incidence of G6PD deficiency in vivax malaria patients is low." (PMID 30882150, 2019). "Although reported to be safe, MB is contraindicated in patients suffering from renal insufficiency, glucose-6-phosphate dehydrogenase (G6PD) deficiency, and Heinz body anaemia." (PMID 31030340, 2019). "Because males are both phenotypically and genotypically either G6PD deficient or normal, it is most reliable to express G6PD deficiency prevalence based on the male G6PD deficiency prevalence." (PMID 30184203, 2019). "Although the WHO recommends that patients be tested for G6PD deficiency prior to administration of primaquine, in reality, G6PD testing is rarely available in poorly resourced endemic regions." (PMID 30940140, 2019). "The study characterized the three most common mutations in the G6PD gene among Filipinos with G6PD deficiency." (PMID 33072985, 2019). "Owing to the high prevalence of G6PD deficiency in the Greater Mekong Subregion, strategies for vivax malaria elimination should include point-of-care G6PD testing (both qualitative and quantitative) to allow safe and wide treatment with 8-aminoquinolines." (PMID 30674319, 2019). "Before primaquine can be administered to a patient for radical treatment of P. vivax malaria, screening for G6PD activity is required because primaquine is contraindicated in patients with G6PD deficiency." (PMID 31525211, 2019). "To date, more than 150 G6PD variants have been identified as causal or risk factors in G6PD deficiency." (PMID 31862010, 2019). "Malaria causes a reduction in haemoglobin that is compounded by primaquine, particularly in patients with glucose-6-phosphate dehydrogenase (G6PD) deficiency." (PMID 31366382, 2019). "In our study site, G6PD deficiency is observed in about 10% of males, most of whom carry the G6PD A- allele (unpublished data)." (PMID 31836757, 2019). "Among the 100 cases, 86% had normal G6PD levels, 11% had G6PD deficiency and 3% had increased G6PD levels." (PMID 31703724, 2019). "The STANDARD G6PD product represents an opportunity to diagnose G6PD deficiency equally for males and females in basic clinical laboratories in high- and low-resource settings." (PMID 30350771, 2019). "Venous blood samples from 443 healthy blood donors recruited at the National Transfusion Center in Nouakchott were screened for G6PD activity using the CareStart G6PD deficiency rapid diagnostic test." (PMID 31525211, 2019). "Baseline Hb level, parasitemia level, G6PD deficiency, and thalassemia explained 45.4% (R2 = 45.4%) of the change in absolute Hb level, and a higher level of G6PD enzyme activity was associated with a lower change in absolute Hb level (data not shown)." (PMID 31549159, 2019). "Intravascular hemolysis in presence of glucose-6-phosphate dehydrogenase (G6PD) deficiency has been reported rarely in literature." (PMID 31086458, 2019). "This is consistent with the higher susceptibility of males to G6PD deficiency than females owing to the X-linked inheritance G6PD deficient alleles (SNPs) and the hemizygous nature of the X-chromosome in males." (PMID 30819192, 2019).
G6PD deficiency (continued). "PQ and TQ provoke dose-dependent acute hemolytic anemia in patients with glucose-6-phosphate dehydrogenase (G6PD) deficiency, an X-linked recessive, red blood cell (RBC) enzymopathy whose variants have differing degrees of sensitivity to 8-aminoquinolines." (PMID 31549159, 2019). "This is a descriptive study that describes the mutations detected by whole gene sequencing of the G6PD gene among 106 Filipino children aged 0–12 months old with G6PD deficiency." (PMID 33072985, 2019). "In this study, two tests for G6PD deficiency were evaluated against the gold standard laboratory quantitative assay for G6PD activity (Pointe Scientific) combined with the gold standard hemoglobin assay (HemoCue)." (PMID 30350771, 2019). "Even though G6PD deficiency is largely asymptomatic, acute haemolytic anaemia can be triggered among G6PD deficient individuals by an infection, ingestion of fava beans or certain drugs." (PMID 30819192, 2019). "In Bangladesh, a prevalence of 17.4% (173/995) for G6PD deficiency (< 60% of the adjusted male median G6PD activity) was reported using standard UV spectrophotometry." (PMID 31590661, 2019). "Low glucose-6-phosphate dehydrogenase activity level (LG6PD) is one of typical features of G6PD deficiency, which is an X-linked incomplete dominant inheritance of red blood cell enzyme disease, as well as one of the most common causes of hemolytic anemia." (PMID 30846733, 2019). "Classification of glucose-6-phosphate dehydrogenase deficiency (G6PDD) with respect to glucose-6-phosphate dehydrogenase (G6PD) activity." (PMID 33072997, 2019). "As a consequence of the poor feasibility of performing quantitative testing for G6PD deficiency as part of malaria clinical management to date, G6PD-deficiency-associated risk in females is poorly understood and perhaps underestimated." (PMID 30184203, 2019). "A 14-day course of primaquine was recommended to complete radical cure of vivax malaria, but this drug can cause a serious side effect, e.g., from mild to severe hemolysis in patients with glucose-6-phosphate dehydrogenase (G6PD) deficiency." (PMID 30700970, 2019). "A framework for assessing the cost-effectiveness for G6PD testing at birth in settings with high prevalence of G6PD deficiency and other triggers for G6PD deficiency–associated hemolysis should be considered." (PMID 31709308, 2018). "On the other hand, HRM-based genetic testing that conformed to the Sanger sequencing data revealed that 9 of the 63 participants were carrying G6PD gene variants that cause G6PD deficiency, one in homozygous state and eight in heterozygous states." (PMID 30097005, 2018). "The gene coding for the enzyme is on the X—chromosome (Xq28); to date more than 185 G6PD clinically relevant variants have been described that result in varying degrees of reduced G6PD activity, collectively called G6PD deficiency (G6PDd)." (PMID 29929514, 2018). "A total of 30 out of 910 samples sequenced from males (3.5%; 95% CI 2.2–5.4%) had a G6PD variant allele associated with G6PD deficiency, with the majority being the Union and Viangchan polymorphisms, with smaller numbers of Canton and Mahidol." (PMID 29859089, 2018). "Later, Brewer’s test and quantitative assay of G6PD levels confirmed the diagnosis of G6PD deficiency." (PMID 29540210, 2018). "G6PD deficiency can be caused by several mutations in the G6PD gene which cause protein instability and decreased enzymatic activity." (PMID 29738562, 2018). "The CareStartTM G6PD deficiency RDT was able to detect all the genetically-determined G6PD-deficient hemizygous males and homozygous females with the highest risk of haemolysis." (PMID 29558929, 2018). "G6PD deficiency, an X-linked incomplete dominant hereditary disease, is caused by deficiency of the enzyme G6PD due to G6PD gene mutations." (PMID 30298137, 2018). "From a clinical perspective, it is the G6PD phenotype that informs the risk of someone developing G6PD deficiency–related pathologies." (PMID 31709308, 2018).